CD86 (CD86 molecule)
Diseases named in the same sentence as CD86 in open-access papers (continued):
Sharing a sentence is not in itself a finding about the gene and the disease.
Obesity (29 papers, 2013 to 2024). Accumulation of substantial excess body fat. "In apparent conflict with a protective role for CD80/CD86 in obesity-associated IR, one group of investigators reported that CTLA-4-IgG1 administration improved insulin sensitivity in DIO mice." (PMID 26146464, 2015). "However, expression of the obesity-associated macrophage marker CD11c was reduced in CD11cΔLKB1, while the absolute number of CD11c+ macrophages per gram eWAT and CD86 expression were unchanged." (PMID 37140993, 2023). "Insulin resistance has been associated with ATM MHC II antigen presentation in murine obesity and in human CD11c+ ATMs, so we examined antigen presentation–related genes HLA-D, CD40, CD80, CD86, and ICAM1 in ATM subtypes." (PMID 34990410, 2022). "In our previous investigation, we also elucidated a homeostatic role of B7-mediated co-stimulation in diet-induced obesity using CD80/CD86 double knockout (B7 KO) mice and investigated the relevance of this process in humans with obesity and IR." (PMID 29416823, 2018). "In their data set, 11 of 15 genes involved in MHC-II antigen presentation, 3 of 5 involved in MHC-II antigen processing, and the costimulatory molecule CD86 increased with obesity." (PMID 26146464, 2015). "Notably, obesity significantly increased the number of CD86-positive M1 macrophages in adipose tissues, whereas GABA treatment reduced inflammation and proinflammatory M1 macrophages in the iWAT of the HFD group." (PMID 36678326, 2023). "Morbid obesity, regardless of the degree of insulin resistance, was associated with changes in the expression of genes involved in pro- (such as CD86 and S100A8) and anti-inflammatory (such as CCL18 and ZBTB16) responses." (PMID 35625760, 2022). "Our results concerning monocyte CD36 and CD86 expression suggest an influence of obesity." (PMID 31936430, 2020). "The hub genes calculated by Cytoscape software are MNDA (score 320), CYBB (score 314), CD86 (score 312), FCGR2C (score 242), NCF2 (score 240), LCP2 (score 182), TLR8 (score 148), HLA-DRA (score 54), LCP1 (score 30), and PTPN22 (score 8), which are considered to be associated with obesity-related AF." (PMID 36671813, 2023). "In line with T cell inflammation in adipose tissue, obesity increased the expression of antigen presenting molecules MHCI and MHCII and co-stimulatory molecule CD86 on macrophages and CD86 on B cells." (PMID 31736971, 2019). "Next, we found that the increased TLR8 gene expression in the adipose tissues in obesity/T2D paralleled with enhanced expression of monocyte/macrophage markers such as CD68, CD11c, CD86, and CD163." (PMID 27980459, 2016). "In obesity, CD80 and CD86 gene expression have been shown to be increased in obese human and mouse adipocytes." (PMID 26146464, 2015). "Similarly, in obesity, collagen VI expression in omental white adipose tissue is correlated with expression of MCP-1, CD68, and CD86, providing further evidence that this collagen influences macrophage infiltration and phenotype." (PMID 36901727, 2023). "While Cd86 gene expression increased following obesity, no change in Cd80 mRNA or protein expression was observed due to diet within the classical monocyte subcluster." (PMID 35618862, 2022). "Macrophages from mothers with obesity failed to induce CD86 upregulation following IFNγ stimulation (right), while HLA-DR induction was comparable between the two groups." (PMID 34195568, 2021). "There were no significant changes in CD86 expression in obesity and T2DM when compared to PBMC of lean subjects." (PMID 30356719, 2018). "CD4+ and CD8+ T cells populate the human adipose tissue and the Th1:Th2 balance is highly associated with systemic inflammation and insulin resistance; in addition, MHCII and costimulators CD86 and CD40 play essential roles in obesity-induced adipose tissue inflammation." (PMID 29765984, 2018).
Obesity (continued). "Since both obesity and T2DM are pro-inflammatory states, we examined the expression of several M1 phenotype markers in PBMC of lean, obese, T2DM, and T2DM on Metformin, including CD86, CD11c, CD169, IL-6, TNFα, iNOS, and CD36." (PMID 30356719, 2018). "Additionally, obesity induced the expression of MHC-II and CD86 in all APCs in both VAT and SAT." (PMID 38566998, 2024). "CD86, a protein expressed by antigen-presenting cells to modulate T cell activity, shows an expression pattern opposite to the one observed in obesity in vivo, which might be accounted for by the lack of T cells in the culture." (PMID 34608215, 2021). "Furthermore, within the population of macrophages with high CD206 expression, there was higher expression of CD11b, CD11c, CD32, CD80, CD86, CD163, CD192, and HLA-DR in obesity, suggesting that these macrophages were activated and shared components of both classical M1 and M2 expression patterns." (PMID 30719456, 2019). "Interestingly, as in obesity, ATMs in CLS were predominantly positive for the commonly used M1 markers CD11c, CD86, and CD9, whereas interstitial ATMs showed almost no expression of these marker proteins." (PMID 34091595, 2021).
Stroke (29 papers, 2010 to 2025). Sudden impairment of blood flow to a part of the brain due to occlusion or rupture of an artery to the brain. "Our findings highlight the causal role of p21+CD86+ microglia in neuroinflammation and uncover novel therapeutic targets to enhance recovery in stroke patients." (PMID 40585759, 2025). "CD19 + CD86 + B cells are associated with pro-inflammatory factor release, carotid artery stenosis, and high risk of stroke." (PMID 38221996, 2023). "Transcriptional analysis confirmed a reduction in expression of co-stimulatory genes in the spleen known to be expressed by macrophages 1–5 days after experimental stroke including Cd40, Cd80, Cd86, Icam1, Tnfsf9, which encodes 4-1BBL, and Cd274." (PMID 29872438, 2018). "Our preclinical findings lay the foundation for targeting p21+CD86+ microglia as a novel therapeutic strategy, highlighting the potential of exosome‐based senolytic anti‐inflammatory therapy for stroke and other central nervous system disorders." (PMID 40585759, 2025). "We identified a harmful immune cell type, p21+CD86+ microglia, driving post‐stroke inflammation and developed a targeted exosome‐based therapy (Que@micro‐Exo) to eliminate these cells." (PMID 40585759, 2025). "In CD57BL/6 mice exposed to MCAO, CD206+ microglia and macrophages gradually accumulate in ischemic brain tissue during the first-week post-stroke, subsequently replaced by CD86+ microglia and macrophages." (PMID 35669105, 2022). "Stroke induced an increase in the ratio of the proinflammatory (M1-like) CD86+ compared to the anti-inflammatory (M2-like) CD 206+ microglia/macrophages." (PMID 33572986, 2021). "PD-L1 and CD86 were inversely correlated with age on day 5 after stroke in the unstimulated cells (PD-L1: r = −0.6344, p = 0.0298; CD86: r = −0.6658, p = 0.0181)." (PMID 33329318, 2020). "Expression of the activation markers CD80 and CD86 after stroke remained unaffected by vehicle and t-PA treatment on cDC and macrophages from the cLN at the 24 h time point (data not shown)." (PMID 30972077, 2019). "The observed increase in activated M1 cells at day 4 post-stroke was further confirmed by transcript analysis of perilesional areas of the M1 marker Cd86/B7-2 (P < 0.001)." (PMID 29342151, 2018). "In this study, for the MCAO-veh group, M1 genes including CD16, CD32, and CD86 increased soon after stroke and remained high at 72 h." (PMID 25889216, 2015). "Cd86 is a classic marker of the M1 phenotype, which has been widely considered to contribute to brain injury and is significantly increased in brains after stroke." (PMID 40777042, 2025). "Furthermore, the number of CD86+ B cells correlates with increased stenosis and a higher incidence of stroke in humans." (PMID 40805981, 2025). "In a large human follow-up study, different roles have been identified for the expression of CD86 and CD40 on peripheral B cells; whereas high levels of CD19+CD40+ B cells were associated with a decreased risk of stroke, the opposite association was found for CD19+CD86+ cells." (PMID 33572939, 2021). "Interestingly, ONO-AE1-259-01 has been suggested to elevate cAMP and inhibit expression of inflammatory molecules such as ICAM-1 and B7.2 (CD86), and such inflammatory molecules affect stroke outcomes." (PMID 20615245, 2010). "Stroke increased the expression of inflammatory genes, including pro-inflammatory IBA1, IL-6, CD86, and anti-inflammatory CD206 (infarcted vs. non- infarcted, one-way ANOVA)." (PMID 36812289, 2023). "The double‐stained cells showed different trends in the intensity levels for CD86+/Iba‐1+ (5960.95 ± 1466.21% vs 11 520.42 ± 1279.07%, stroke/PBM and stroke/control, respectively, p < 0.001)." (PMID 35076161, 2022). "As presented, the visualized images substantiated clearly different intensity levels for the Iba‐1+, CD86+/Iba‐1+, and CD206+/Iba‐1+ cells in the stroke/control groups compared to the sham/control groups." (PMID 35076161, 2022).
Stroke (continued). "The expression of M1 (MCP-1, iNOS, CD32, CD86 and IFN-γ) and M2 (Ym1/2, Arg-1, CD206, BDNF and TGF-β) markers was significantly increased in vehicle-treated stroke mice 1, 3, 7, and 14 days after MCAO." (PMID 31434993, 2019). "Moreover, IRG1−/− stroke animals displayed elevated microglia activation, demonstrated with increased CD68, CD86 and Iba1 expression." (PMID 34557667, 2021). "Moreover, we further detected the temporal profiles when infiltrating immune cells defined as CD45high cells, macrophages, and CD68+, CD86+, and CD206+ macrophages were present in the ischemic brain at 1, 3, and 7 days following stroke." (PMID 32867781, 2020). "The mRNA levels of M2 markers (Arg-1, Ym-1) increased at 24 h, peaked at 3 d after stroke and then began to decrease; while the mRNA levels of M1 markers (CD16, CD86) gradually increased over time from 3 d and remained elevated for at least 14 days after tMCAO28." (PMID 27775054, 2016). "Thus, it is possible that IFNAR1 signaling induces STAT3 activation, leading to the suppression of tPA-enhanced inflammatory molecules, IL-1α, IL-1β and CD86, expression and the promotion of anti-inflammatory molecules, Arg1 and CD206, upregulation in MG in delayed tPA-treated stroke animals." (PMID 37063896, 2023).
leukemia (28 papers, 2008 to 2025). A malignant (clonal) hematologic disorder, involving hematopoietic stem cells and characterized by the presence of primitive or atypical myeloid or lymphoid cells in the bone marrow and the blood. "The high levels of CD86 are found in leukemia and leads to inactivation of T cells and relapse risk, whereas, expression of CD40 has diverse effects on cell functions to induce immune response." (PMID 40896706, 2025). "For other myeloid cell populations in CLL, the percentage of leukemia-associated neutrophils expressing CD86 is increased at the advanced stage of leukemia." (PMID 37817276, 2023). "The group with high CD86 expression had a higher risk, indicating that the high CD86 level was a risk factor for leukemia." (PMID 37064861, 2023). "In this study, we collected LEXs derived from mouse leukemia L1210 cells transduced with a lentiviral vector encoding CD80 and CD86 and investigated the anti-leukemia immunity of LEX-CD8086-targeted CD4+ T cells in vitro and in vivo." (PMID 36466863, 2022). "We used lentiviral vectors encoding CD80 and CD86 to successfully transduced the L1210 leukemia cells, and the expression of CD80 and CD86 was remarkably upregulated in leukemia cells." (PMID 36466863, 2022). "In this study, CD80 and CD86 were overexpressed in L1210 leukemia cells through transduction of lentiviruses encoding CD80 and CD86." (PMID 32578140, 2020). "Lentivirus-mediated transduction of L1210 leukemia cells produced exosomes (LEXs) enriched with CD80/CD86, which enhanced dendritic cell activation, promoted Th1 cytokine production, and induced leukemia-specific cytotoxic T lymphocyte responses." (PMID 41426784, 2025). "Seven leukemia-associated immunophenotype pattern (LAIP) markers, CD9, CD44, CD58, CD73, CD81, CD86, and CD123, were also included in the diagnostic panel." (PMID 39371707, 2024). "Altogether, these data suggest that obtaining LEX highly expressing CD80 and CD86 through the costimulatory molecule gene-modified leukemia cells is feasible." (PMID 36466863, 2022). "The LEXs highly expressing CD80 and CD86 were obtained from the supernatants of gene-transduced leukemia cells." (PMID 36466863, 2022). "To upregulate the expression of costimulatory molecules on leukemia cells, we constructed a lentiviral vector encoding the CD80 and CD86 genes." (PMID 36466863, 2022). "In this study, we show that the B7 costimulatory molecules CD80 and CD86 exhibit a low expression on L1210 leukemia cells and its exosomes (LEXs)." (PMID 32578140, 2020). "In summary, our results indicate that modified LEXs overexpressing CD80 and CD86 can induce a more powerful immunity against leukemia cells." (PMID 32578140, 2020). "These proteins included the myeloid differentiation marker CD86 and the leukemia cell-specific HAVCR2/TIM-3." (PMID 31336716, 2019). "For example, the combination of GM-CSF, IL-4, and TNFα induced the expression of MHC II, CD40, CD86, CD1a, CD1b, and CD1c by neutrophil-committed precursors isolated from leukemia patients receiving G-CSF treatments." (PMID 24278484, 2013). "In the case of leukemia, exosomes derived from leukemia cells could be generated using lentiviral vectors encoding CD80 and CD86, two B7 costimulatory molecules." (PMID 38562940, 2024). "We made similar observations in primary patient MLL leukemia cells with upregulation of differentiation markers CD11b and CD86, reduced clonogenic activity, increased maturation of cells to mature macrophages and a G1 cell cycle arrest without significant enhancement of apoptosis." (PMID 36171271, 2022). "In this study, we upregulated the expression of CD80 and CD86 in LEXs through genetically modifying parental L1210 leukemia cells with lentiviruses encoding CD80 and CD86 genes and compared the morphology and typical exosomal proteins on modified LEXs to their unmodified counterpart." (PMID 36466863, 2022).
leukemia (continued). "In this study, we constructed a novel LEX-based vaccine by combining CD4+ T cells with costimulatory molecules gene-modified LEXs, which harbor upregulated CD80 and CD86, and the anti-leukemia immunity of CD80 and CD86 gene-modified LEX-targeted CD4+ T cells was investigated." (PMID 36466863, 2022). "In addition, elevated levels of soluble CD80, and CD86 in some leukemia patients have been demonstrated, and elevated sCD86 levels have been reported as a marker of poor prognosis in acute myeloid leukemia." (PMID 23049754, 2012). "Other studies reported satisfactory anti-leukemia responses using leukemia cell-derived EVs engineered to express high levels of the co-stimulatory molecules CD80 and CD86, or low levels of PDL-1." (PMID 40508186, 2025). "DBA/2 mice immunized with leukemia-derived EVs rich in CD80 and CD86 demonstrated dramatically better survival when exposed to L1210 cells than when the mice were immunized with unaltered leukemia-derived EVs." (PMID 37822925, 2023). "Taken together, our data suggest that leukemia cells can be genetically modified to upregulate CD80 and CD86 expression in LEXs." (PMID 36466863, 2022). "LEX-CD8086 transfers its intrinsic LAA and molecules and acquired costimulatory CD80 and CD86 molecules to CD4+ T cells, making CD4+ TLEX-CD8086 cells both Th1 cells and APCs capable of inducing efficient leukemia antigen-specific CD8+ CTL response." (PMID 36466863, 2022). "In carnosine-treated cells, differentiation and phenotype are altered, increasing expression of CD11b, CD11c, CD86, and MHCII, thus enabling the promonocytic leukemia cells to be more visible to the immune system." (PMID 33809496, 2021). "We found that transduced leukemia cell-derived LEXs (LEX-CD80, LEX-CD86, LEX-CD8086) carried ectopic levels of CD80 and CD86." (PMID 32578140, 2020). "Of note, TRuC-T cells cleared tumor in a Nalm6 leukemia model, which is known for its low expression of co-stimulatory ligands CD80 and CD86." (PMID 31064990, 2019). "Mass cytometry further revealed that YW3-56 treatment simultaneously suppresses leukemia stemness (CD44/CD133 downregulation) and promotes myeloid differentiation (CD11b/CD14 upregulation), as well as enhances immunogenic activation (CD80/CD86 increase)." (PMID 41304891, 2025). "Similarly, another study aimed to improve anti-leukemia immune responses using leukemia cell-derived EVs loaded onto DCs modified to express co-stimulatory molecules CD80 and CD86 (LEX-8086)." (PMID 39572459, 2024). "For instance, it has been reported that THP-1 cells and the CD34 + (KG-1) leukaemia cell line incubated with varying concentrations of rhGM-CSF and rhIL-4 for 5 days showed upregulated levels of CD11c, CD80 and CD86 and of the cell-surface receptors CD40, CD209 (DC-SIGN) but failed to express CD83." (PMID 34800147, 2022). "Our data showed leukemia cells could be genetically modified to upregulate CD80 and CD86 expression in LEXs." (PMID 36466863, 2022). "Moreover, upregulation of CD80 and CD86 expression in LEXs more effectively promoted DC maturation, CD4+ T cell proliferation, and Th1 cytokine secretion, thus inducing a stronger leukemia antigen-specific anti-leukemia CD8+ CTL response than LEX alone did." (PMID 36466863, 2022). "CTLA-4/CD80/CD86—hampering T cell immunity against hematological malignancies and modulating immune responses in AML.Blocking of CTLA-4 pathway—increase of anti-leukemia T-cell immune response translated in prolonged tumor regression." (PMID 31649875, 2019). "Blockade of CD86 signaling partially impaired CTL killing of THP-1 cells, indicating that increase in CD86 expression induced by HDAC inhibition participated in observed anti-leukemia immune response." (PMID 23940586, 2013).
leukemia (continued). "Although all mice immunized with LEX-CD8086 more obviously reduced tumor burden than LEX-null and PBS did, none showed long-term survival, suggesting that the upregulation of CD80 and CD86 expression alone in LEX-based vaccines may still not be sufficient to inhibit leukemia progression." (PMID 36466863, 2022). "IFN-γ KO/KD also did not decrease the efficacy of anti-CD19 CAR Ts against leukemia/lymphoma models, while decreased the levels of some inflammatory cytokines (MCP-1, MIP-1β, IL-6, TNF-α, and IP-10) and macrophage activity markers (CD80 and CD86)." (PMID 41354926, 2025).